IGF1 (insulin like growth factor 1)
Diseases named in the same sentence as IGF1 in open-access papers (continued):
Sharing a sentence is not in itself a finding about the gene and the disease.
Cirrhosis (continued). "Although liver synthesizes IGF-1, IGF-2 and their binding proteins (IGFBPs) at a high level under the normal condition, the expression levels significantly decrease under pathogenic conditions like non-alcoholic fatty liver disease (NAFLD), cirrhosis, and HCC." (PMID 30700007, 2019). "Hence, it was concluded that rSV40-mediated, sustained expression of IGF1 in the liver slowed cirrhosis progression." (PMID 29702590, 2018). "Also, similarly to IGF1 levels, differences in concentrations between clinical categories of cirrhosis (Child Pugh score) were observed." (PMID 29702590, 2018). "Additionally, one clinical trial in patients with cirrhosis of different etiologies demonstrated a significant increase of albumin serum levels when administered IGF-1." (PMID 28124277, 2017). "Additionally, patients with cirrhosis had lower circulating IGF1 and IGFBP3 levels than healthy controls (p < 0.001)." (PMID 29113370, 2017). "Results in this paper demonstrate that low doses of IGF-1, for short periods of time, induce hepatoprotective, antioxidant, and antifibrogenic effects in animals with acute liver damage, in accordance with previous results from experimental cirrhosis." (PMID 28472963, 2017). "Furthermore, another murine study of CCl4-induced-cirrhosis suggested that IGF-1 treatment improves the polarity of hepatocytes and intercellular unions, leading to an improvement of liver architecture." (PMID 28124277, 2017). "Moreover, our group has previously reported that, in an experimental cirrhosis model, low doses of IGF-1 improved nitrogen balance, jejunal sugar and amino-acid absorption, osteopenia, testicular atrophy, and somatostatinergic tone." (PMID 28472963, 2017). "Secondly, IGF-1 exogenous administration could be a strategic therapy in the early stages of liver damage, avoiding the progression to cirrhosis." (PMID 28472963, 2017). "With an increase in age of patients with cirrhosis, a decrease in IGF-1 levels was observed." (PMID 23599716, 2013). "In a similar study in 2003, 40 patients with advanced viral and alcoholic cirrhosis and primary biliary cirrhosis with variable severity according to Child staging were evaluated in which the level of IGF-1 was inversely related to the degree of splenomegaly and the severity of cirrhosis." (PMID 23599716, 2013). "In alcoholics with cirrhosis, the reduced bioavailability of insulin-like growth factor 1 (IGF1) due to liver disease could partly contribute to increased blood levels of estradiol and estrone and the onset of hypogonadism, given the stimulatory activity of IGF1 on testosterone synthesis." (PMID 39590862, 2024). "Similarly, IGF-1 administration improved liver function (increased albumin, total protein, and coagulation factor levels) and reduced oxidative liver damage and fibrosis in rat models with CCl4-induced cirrhosis." (PMID 37554499, 2023). "Finally, through mechanisms not yet completely elucidated, cirrhosis is associated with a state of GH resistance, with high circulating GH and low circulating IGF-1." (PMID 37520312, 2023). "However, previous studies were limited to decompensated cirrhosis or short-term research duration and have not yet reported the association of IGF-1 with long-term prognosis in patients with compensated and decompensated cirrhosis, respectively." (PMID 37554499, 2023). "Reportedly, serum IGF-1 levels are substantially low in a large percentage of patients with compensated cirrhosis despite normal albumin and prealbumin levels; hence, they may be a more sensitive and earlier indicator of impaired liver function than other conventional parameters." (PMID 37554499, 2023). "Thus, circulating IGF-1 levels may be useful for estimating liver functional reserve or pathological condition and predicting prognosis in patients with cirrhosis." (PMID 37554499, 2023).
Cirrhosis (continued). "Therefore, IGF-1 may be useful for predicting decompensation-related events and should be regularly monitored in the management of compensated cirrhosis." (PMID 37554499, 2023). "The anomalies of the Growth Hormone (GH)/Insulin-like Growth Factor-1 (IGF1) axis are associated with a higher prevalence of Metabolic Associated Fatty Liver Disease (MAFLD) and with a more rapid progression towards fibrosis, cirrhosis, and end-stage liver disease." (PMID 36557260, 2022). "However, in patients with cirrhosis, despite the increase in circulating GH levels, serum IGF1, IGFBP3 and ALS levels and the IGF1 response to GH were found to be lower than in controls, resembling a condition of GH resistance, as a consequence of liver dysfunction." (PMID 25225571, 2014). "Preoperative serum IGF-1 and IGF-binding protein-3 levels in the cirrhosis group who underwent liver transplantation were lower than those in the control group, but their postoperative levels recovered to normal." (PMID 37554499, 2023). "Multiple intracellular signaling pathways such as the IGF1/AKT, myostatin, cytokine/NFκB, and AMPK pathways interact and regulate muscle mass and protein metabolism, which are disrupted in cirrhosis." (PMID 31392488, 2019). "The increased rate of serum IGF1/IGFBP3 is described in patients with HCC, compared to patients with cirrhosis and liver failure." (PMID 29702590, 2018). "With the exception of the first study (IGF-1), all these studies were performed in a retrospective manner and demonstrated the ability to discern established HCC from cirrhosis." (PMID 29872158, 2018). "This is likely because of reduced secretion of the liver-derived factors IGF1 and IGFBP3 in cirrhosis and HCC patients with chronic liver damage and functional insufficiency." (PMID 29113370, 2017). "The geometric mean serum levels of IGF1 and IGFBP3 differed significantly among the healthy, cirrhosis, and HCC groups independently of the degree of impairment of liver function." (PMID 29113370, 2017). "The geometric mean and standard deviation (SD) of serum IGF1 and IGFBP3 levels in the healthy, cirrhosis, and HCC groups were calculated." (PMID 29113370, 2017). "To expand these results, we performed comparative analysis of TLR7, LC3A/B, and IGF-1 in mice under normal, NAFLD, and cirrhosis conditions." (PMID 27279075, 2016). "To investigate hepatic IGF-1 content in all stages of chronic liver disease, we performed comparative analysis of protein expression of TLR7, LC3A/B, and IGF-1 in livers from mice under normal, NAFLD, and cirrhosis conditions." (PMID 27279075, 2016). "In patients with hepatitis C virus–related cirrhosis, HCC development was accompanied by significant reduction in serum IGF-1 levels." (PMID 24586785, 2014). "In summary, metabolic dysfunction that influences liver health, which can lead to cirrhosis, includes altered fatty acid oxidation, the appearance of mediators such as TNF-α and IL-6, a reduction in the liver synthesis of insulin-like growth factor-1 (IGF-1), and insulin resistance in the liver." (PMID 40806358, 2025). "In cirrhosis, particularly in advanced stages (Child-Pugh Class B and C), circulating levels of IGF-1 have been shown to be significantly lower compared to non-cirrhotic individuals." (PMID 40806358, 2025). "Compared with normal subjects, serum IGF-1 level is much lower and IL-6 levels were much higher in patients with cirrhosis, and there was a negative correlation between levels of IGF-1 and IL-6." (PMID 37881635, 2023). "Another study of patients with decompensated cirrhosis (without HCC) revealed that serum IGF-1 levels (median: 70.1, 40.5, and 32.4 ng/mL for CP class A, B, and C, respectively) and IGF-CP scores were associated with 1 year mortality." (PMID 37554499, 2023). "Intriguingly, serum IGF-1 levels were the only significant prognostic factor in patients with compensated cirrhosis, whereas serum albumin (but not IGF-1) levels in those with decompensated cirrhosis." (PMID 37554499, 2023).
Cirrhosis (continued). "This study revealed that patients with cirrhosis had significantly lower serum IGF-1 levels than those without cirrhosis." (PMID 36010307, 2022). "In animal models, IGF-1 treatment improved non-alcoholic steatohepatitis (NASH) and cirrhosis." (PMID 32050952, 2020). "Higher IGF-1 levels were found in HCC developing in non-cirrhotic liver compared to patients with cirrhosis (median (range) 61.1 ng/mL (17.4–230.5 ng/mL) vs. 39.0 ng/mL (9.6–239.6 ng/mL); p < 0.01)." (PMID 30064393, 2018). "Serum IGF-1 levels were significantly lower in patients with HCC in cirrhosis compared with non-cirrhotic HCC (p < 0.01)." (PMID 30064393, 2018). "Accordingly, serum contents of IGF-1 decreased in both NAFLD and cirrhosis." (PMID 27279075, 2016). "HCC associated with cirrhosis, regardless of HBV and HCV infection, is characterized by significantly lower levels of serum IGF1 than healthy subjects." (PMID 25225571, 2014). "We therefore hypothesize that this high IGF1+IGF2/IGFBP3 molar ratio, resulting in high total (IGF1+IGF2) bioavailability, could slow down the evolution form HS to fibrosis or cirrhosis." (PMID 25117570, 2014). "Expression of IGF-1 was low in adjacent liver in 6 of 10 patients with cirrhosis, compared with 2 of 17 patients without cirrhosis (P = 0.025)." (PMID 25052889, 2014). "In this report, IGF-1 expression in adjacent non-neoplastic liver was low in patients with cirrhosis compared with noncirrhotic patients." (PMID 25052889, 2014). "Expression of IGF-1 was low in non-neoplastic liver in 6 of 10 patients with cirrhosis, compared with 2 of 17 patients without cirrhosis (P = 0.025)." (PMID 25052889, 2014). "Furthermore, the median IGF-1 level was significantly higher in patients without cirrhosis (92.5 ng/ml) than those with cirrhosis (56.8 ng/ml), with a p-value of 0.0395." (PMID 39624154, 2025). "Furthermore, combined serum IGF-1 levels and CP scores (IGF-CP score) more accurately predict 1 year mortality than CP or model for end-stage liver disease (MELD) scores alone in patients with decompensated cirrhosis." (PMID 37554499, 2023). "Among the conditions that could modify the serum concentrations of IGF-1, we could also mention the association between cardiac decompensation and hepatocellular dysfunction, having cirrhosis a negative effect on IGF-1 peripheral secretion." (PMID 35445917, 2022). "Furthermore, serum IGF-1 levels were significantly lower in patients with HCC developing in cirrhosis compared with non-cirrhotic HCC." (PMID 30064393, 2018). "In men with AUD and cirrhosis, a decrease in IGF-1 bioavailability as a result of liver disease contributes at least in part to the elevated circulating levels of estradiol and estrone and the development of hypogonadism since IGF-1 can stimulate testosterone synthesis and spermatogenesis." (PMID 28988577, 2017). "The IGF-1 predictive value of poor prognosis in patients with cirrhosis (without HCC) may be approximately 40 ng/mL, considering that the cutoff IGF-1 values for the L-IGF1 groups were 41, 47, and 32 ng/mL in all patients and those with compensated and decompensated cirrhosis, respectively." (PMID 37554499, 2023). "By contrast, IGF1 showed a mirror image being significantly reduced in HCC, cirrhosis and PBC, but not in CAH." (PMID 41751398, 2026). "However, IGF-1 expression was increased in NAFLD, but not cirrhosis." (PMID 27279075, 2016).
dementia (74 papers, 2009 to 2026). Loss of intellectual abilities interfering with an individual's social and occupational functions. "IGF-1 (insulin-like growth factor-1) is implicated in the etiology of dementia, protects neurons by lowering their sensitivity to oxidative stress, and is strongly correlated with the A allele of the IGF1R polymorphism for VAD." (PMID 38384571, 2024). "Survival analyses from CSF proteomics from the Knight ADRC identified several synaptic genes associated with an increased risk of dementia, such as IGF1, NRXN3, and YWHAZ." (PMID 38687811, 2024). "An increase in the cGP/IGF-1 molar ratio with age is associated with normal cognition, whereas a decrease in this ratio with age is associated with dementia in Parkinson disease." (PMID 36770687, 2023). "A previous study of 3582 participants from Framingham reported that lower IGF-1 concentrations were associated with an increased risk of dementia." (PMID 37608387, 2023). "In our study, notably, we observed a threshold effect where both lower and higher IGF-1 concentrations were associated with an increased risk of dementia." (PMID 37608387, 2023). "Less is known about the prospective associations between IGF-1 concentrations and risk of dementia in a general population." (PMID 37608387, 2023). "Numerous studies related to insulin/insulin-like growth factor 1 (IGF-1) signaling are linked with various types of dementia." (PMID 37511207, 2023). "The development of multi-target drugs for dementia treatment aligns with the concept of repositioning anti-diabetic drugs for dementia, as the insulin/IGF-1 signaling pathway has been implicated in the majority of dementia subtypes." (PMID 37511207, 2023). "While IGF‐1 can protect against dementia in younger individuals, it is conversely associated with an increased risk of dementia in the elderly." (PMID 35927253, 2022). "Therefore, the decline of IGF-1 can affect the activity of neurons, leading to amyloidosis, cognitive deficits, loss of synaptic vesicle protein, and ultimately the development of dementia." (PMID 40491991, 2025). "Increased serum levels of IGF-1 might be linked to dementia pathologies, as IGF-1, with its potential to enhance amyloid-beta clearance from the brain, plays a crucial role in improving cognitive functions." (PMID 39407758, 2024). "In contrast, low levels of serum IGF-1 are a risk factor for dementia." (PMID 39407758, 2024). "However, few studies have uncovered the detrimental effect of high IGF-1 concentrations on the risk of dementia." (PMID 37608387, 2023). "This point was discussed also by L. Moll and M. Schubert that reviewed the literature dealing with the role of insulin and insulin-like growth factor-1 in the pathogenesis of obesity-associated dementia, with focus on the possible contribution of forkhead-box transcription factors (FoxO)." (PMID 22761616, 2012). "Furthermore, increased serum IGF-1 levels may lower the risk of developing dementia, as IGF-1 is involved in the removal of beta amyloid from the brain." (PMID 35206577, 2022). "Thus, low concentrations of circulating IGF-1 could serve as a risk factor for the development of AD and other types of dementia." (PMID 35832183, 2022). "In addition, the insulin/IGF1 signaling pathways have been implicated in dysregulated synaptic maturation and may play key roles in brain aging and dementia as well as learning and cognitive functions in rodent models." (PMID 27370225, 2016). "High-frequency keywords included IGF-1, AD, brain, insulin, controlled study, metabolism, oxidative stress, animals, signal transduction, amyloid beta protein, dementia, aging, and neuroprotection." (PMID 41868495, 2026). "This suggests the potential role of IGF-1 as a novel therapeutic target, also in combination with insulin, in the treatment of dementia in sporadic Alzheimer’s disease." (PMID 40283962, 2025).
dementia (continued). "Our results showed that 11 of 13 (84%) proteins encoded by synaptic genes including IGF1, NRXN3, and YWHAZ were associated with an increased risk of dementia progression." (PMID 38687811, 2024). "We also describe the molecular perspectives of various types of dementia through the insulin/IGF-1 signaling pathway." (PMID 37511207, 2023). "Meta-analysis focused on IGF-1 levels in AD patients revealed that individuals with dementia or AD had lower levels of circulating IGF-1 than healthy individuals." (PMID 36755922, 2023). "In comparison with non-dementia controls, down-regulation of IGF1 in AD was also observed in training sets, including GSE5281 (AD: 4.76 ± 1.27 vs. controls: 6.63 ± 0.90; p < 0.001) and GSE37264 (AD: 5.04 ± 1.07 vs. controls: 5.99 ± 0.54; p = 0.04)." (PMID 35571248, 2022). "In test set of GSE132903, the expression level of IGF1 was significantly down-regulated in temporal lobes of 97 AD patients (5.38 ± 0.54) compared with 98 non-dementia controls (5.67 ± 0.45; p < 0.0001)." (PMID 35571248, 2022). "The serine-threonine protein kinase B (AKT1/2) and GSK3-β are involved in the brain insulin/insulin-like growth-factor-1 (IGF-1) signaling whose dysregulation correlates with the severity of dementia symptoms in sAD." (PMID 34830036, 2021). "IGF-1R mediates its action via IGF-1, and its depletion is incorporated in the pathogenesis of dementia." (PMID 32802484, 2020). "IGF-1 signaling plays multiple roles in the CNS, and its potential beneficial role in AD and other dementias helps make the case for the IGF system as a therapeutic target in neurodegenerative diseases, including AD16." (PMID 32226608, 2020). "Accordingly, it is necessary to investigate the relationship between exercise-induced IGF-1 and cognition in human samples, since the clinical field requires resources to treat and prevent dementia and improve health, especially during aging." (PMID 29988330, 2018). "In addition, decreased IGF-1 secretion can cause microvascular rarefaction, BBB disruption, and, in some cases, dementia." (PMID 41598223, 2026). "Deletion of the IGF-1 receptor gene (Igf1r) resulted in an almost complete loss of the DG in mice and impaired learning and memory function, leading to dementia, while exogenous IGF-1 enhanced hippocampal neuronal precursor cells proliferation and directed the generation of mature granule cells." (PMID 40283962, 2025). "We found a U-shaped relationship between IGF-1 concentrations and the risk of dementia, with the lowest risk at a nadir IGF-1 of 18 nmol/L (P for non-linearity < 0.001)." (PMID 37608387, 2023). "In contrast, the decrease in the cGP/IGF-1 molar ratio with age in the PD-D group may reverse this effect during the progression to dementia." (PMID 36770687, 2023). "In contrast, the cGP/IGF-1 molar ratio decreases with age in the PD group with dementia (PD-D)." (PMID 36770687, 2023). "In this paper, we highlight the possibility of repositioning anti-diabetic drugs as a strategy for dementia therapy by analyzing clinical trials as well as integrating the molecular perspectives from various types of dementia through the insulin/IGF-1 signaling pathway." (PMID 37511207, 2023). "Beyond that, the restricted cubic spline model showed a significant nonlinear association between IGF-1 (P for non-linearity = 1.1E-05) and risk of dementia, with increases in the gradient of risk at around 18 nmol/." (PMID 35927253, 2022). "According to AUC analysis of test set and validation of training sets, cohort subgroup comparisons revealed that low IGF1 could actually distinguish AD from non-dementia controls, indicating IGF1 to be a molecular target in predicting the onset of AD." (PMID 35571248, 2022). "Insulin-like growth factor-1 (IGF-1) low levels is risk factor for severe CI and dementia." (PMID 35206577, 2022).